TMEM37 (transmembrane protein 37)
Description:
Thought to stabilize the calcium channel in an inactivated (closed) state. Modulates calcium current when coexpressed with CACNA1G (By similarity).
Synonyms: PR; PR1
Tractability: Antibody: UniProt predicts a signal peptide or a membrane-spanning region.
Gene: Protein-coding gene on chromosome 2 (119,429,901 to 119,438,504, forward strand). Ensembl gene ENSG00000171227.
Subcellular location: Membrane
Subcellular location (Human Protein Atlas): Golgi apparatus
Gene Ontology:
Molecular function: calcium channel activity; voltage-gated monoatomic ion channel activity
Biological process: calcium ion transmembrane transport; monoatomic ion transmembrane transport
Cellular component: membrane
Genetic constraint (gnomAD): Loss-of-function variants: 12 observed, 11.62 expected, observed/expected ratio (o/e) 1.03, 90% interval 0.66 to 1.64. The upper end of that interval is the gene's LOEUF score, 1.64, which puts it in group 6 of 6, group 1 being the genes least tolerant of losing a copy. Missense variants: 203 observed, 261.59 expected, observed/expected ratio (o/e) 0.78, 90% interval 0.69 to 0.87. Synonymous variants: 127 observed, 115.34 expected, observed/expected ratio (o/e) 1.1, 90% interval 0.95 to 1.28.
Homologues: Orthologues: chimpanzee TMEM37 (96% identical), macaque TMEM37 (93% identical), rabbit TMEM37 (81% identical), guinea pig TMEM37 (81% identical), mouse Tmem37 (75% identical), rat Tmem37 (72% identical), tropical clawed frog tmem37 (48% identical), zebrafish tmem37 (46% identical).
Diseases named in the same sentence as TMEM37 in open-access papers:
TMEM37 is named in the same sentence as 49 diseases in open-access papers, as found by Europe PMC text mining. Sharing a sentence is not in itself a finding about the gene and the disease. The quoted sentences say what the papers report.
atrial septum defect (1 paper, 2022). "In this study, of approximately 100 kb, which is three genes were found near breakpoints in multiple samples, including schizophrenia‐related gene TMEM37 and atrial septum defect associated gene WDR33." (PMID 35384386, 2022).
hyperglycaemia (1 paper, 2018). "Hence, TMEM37 reduced expression in type 2 diabetic islets may represent a compensatory effort of beta cells in response to prolonged hyperglycaemia." (PMID 29185012, 2018).
insulinoma (1 paper, 2018). "Silencing of either Arg2 or Ppp1r1a in insulinoma INS-1 832/13 cells reduced insulin secretion, while the opposite was observed by silencing Tmem37, consistent with the latter being an inhibitory subunit of voltage-gated calcium channels." (PMID 29185012, 2018).
type 2 diabetes (1 paper, 2018). "Analysis of islet alpha and beta cell-enriched fractions from five non-diabetic and four type 2 diabetic OD by RT-qPCR showed that ARG2, PPP1R1A and TMEM37 were enriched in beta cells and downregulated in type 2 diabetes." (PMID 29185012, 2018).
TMEM37 also shares sentences with these, for which no sentence is quoted: infection (418 papers); viral infection (26); fungal infection (22); leukemia (17); bacterial infection (16); tumor (16); nematode infection (11); prostate carcinoma (9); breast carcinoma (7); Fusarium infection (7); Autoimmunity (6); bladder cancer (6); myeloid leukemia (5); cancer (4); melanoma (4); acute myeloid leukemia (3); myeloid malignancies (3); chronic myelogenous leukaemia (2); colon cancer (2); COVID-19 (2); cyst (2); lung carcinoma (2); Allergy (1); B-cell lymphoma (1); breast tumor (1); glioma (1); hepatoma (1); Immunodeficiency (1); iron deficiency (1); lipid metabolic disorder (1).
A further 15 diseases each share a sentence with TMEM37 in 1 paper.